IL6 (interleukin 6)
Diseases named in the same sentence as IL6 in open-access papers (continued):
Sharing a sentence is not in itself a finding about the gene and the disease.
dengue (continued). "Nonetheless, the use of PBE for dengue treatments needs more attention since IL-6 synthesis in monocyte culture was reported to be age dependent and dengue virus sero-type specific." (PMID 26152209, 2015). "Treg have an impact on the expression of IFN-γ, TNF-α, and IL-6 production in response to dengue antigens in vitro." (PMID 25010330, 2014). "Previous research has shown that some of the cytokines and chemokines released during dengue fever, including Il-6, IL-8 and IL-18, are also seen in preterm delivery." (PMID 25299383, 2014). "High levels of IL-6 and IL-8 were reported in dengue cases with severe plasma leakage and shock and in non-survivors." (PMID 23717702, 2013). "Other studies have also singled out RANTES, IL-6 and/or IL-8 as cytokines elicited by dengue-infected ECs, thus promoting the endothelium as a source of potent chemotactic cytokines in DSS/DHF patients." (PMID 22952474, 2012). "It is interesting to note that IFNγ, IL-6 and IL-8 levels were found to be higher in secondary than primary infections in a recent study of dengue-infected patients in Western India." (PMID 21206915, 2010). "We assessed the levels of inflammatory mediators- IFN-γ, TNF-α, IL-6 and IL-8 in well characterized dengue patients in context to their clinical presentation combined with laboratory findings, the day of illness and the immune status of the patient." (PMID 20090849, 2010). "Cytokines that are undetectable in the blood of healthy individuals are elevated in dengue-infected patients, such as IL-1β, IL-2, IL-6, IL-8, IL-10, IL-13, IL-18, IFNγ, TNFα, and MCP1." (PMID 21206915, 2010). "Assessment of cytokines and their correlation with disease revealed that three cytokines, IFN-γ, IL-6, and IL-8 were significantly elevated in dengue cases as compared to healthy controls." (PMID 20090849, 2010). "In comparison to those with uncomplicated dengue fever, patients with DHF/DSS have higher plasma levels of inflammatory cytokines IL-6, IL-8, and TNFα, and both IL-8 and TNFα levels are independent correlates of dengue disease severity." (PMID 21206915, 2010). "The circulating levels of four cytokines, IFN-γ, TNF-α, IL-6 and IL-8 were assessed in the 221 confirmed dengue cases." (PMID 20090849, 2010). "In summary, higher levels of IFN-γ, IL-6 and IL-8 were observed in dengue cases compared to healthy controls." (PMID 20090849, 2010). "Higher levels of IL-6 (p = 0.018) and IL-8 (p = 0.06) were observed in secondary cases compared to primary dengue cases." (PMID 20090849, 2010). "We observed that cytokine concentrations of IL-1β, IFN-γ, IL-4, IL-6, IL-7, IL-13 and GM-CSF were significantly increased during severe dengue as compared to mild dengue, while MIP-1β levels are higher in mild dengue." (PMID 18578883, 2008). "Co-infections (particularly with other endemic pathogens like leptospirosis or dengue in tropical settings) could independently elevate IL-6, though all included studies required culture-confirmed B. pseudomallei." (PMID 41439926, 2025). "In dengue patients, circulating EVs contribute to immune dysregulation by transporting immunosuppressive molecules, including checkpoint inhibitors such as PD-L1 and anti-inflammatory cytokines like IL-6 and IL-10." (PMID 40573398, 2025). "This study demonstrated that the Th2-biased cytokine storm pattern observed in hTim4 mice with DENV-2 infection, characterized by elevated levels of Il6 (**P = 0.0082), Il9 (P = 0.3965), Il10 (*P = 0.0168), was highly consistent with the serum profiles of clinical dengue fever patients." (PMID 40623122, 2025). "This study highlights the central role of hyperinflammation in determining outcomes from DS; the data suggest that anti-IL-1 and anti-IL-6 immune modulators and Tie2 agonists may be considered as candidates for therapeutic trials in severe dengue." (PMID 38536887, 2024).
dengue (continued). "Our findings highlight the central role of hyperinflammation in determining outcomes from dengue shock; the data suggest that anti-IL-1 and anti-IL-6 immune modulators and Tie2 agonists may be considered as candidates for therapeutic trials in severe dengue." (PMID 38536887, 2024). "The results of this analysis indicate that while patients with both dengue shock and septic shock have evidence of pro-inflammatory hypercytokinaemia, there is a phenotypic difference between the inflammatory response in dengue shock (ferritin predominant) and septic shock (IL-6 predominant)." (PMID 38536887, 2024). "CSJD may interfere with inflammation by releasing IL-6 factor, thus achieving the purpose of treating dengue fever." (PMID 38206728, 2023). "In severe dengue cases, IL-6 is markedly increased in DSS in comparison to DHF (p<0.05)." (PMID 34447698, 2021). "High levels of IL6 might be involved in severe dengue pathogenesis due to its correlation with disease severity." (PMID 34959637, 2021). "As IL-10 was found to be a key cytokine elevated during early illness during acute dengue, we compared the usefulness of IL-10 in predicting those who are likely to develop DHF, along with other key cytokines such as IL-6, TNFα and IL-1β, which cause vascular leak." (PMID 33199778, 2020). "Moreover, pinocembrin and pinostrobin were well known to downregulate pro-inflammatory cytokines (e.g., TNF-α, IFN-γ, IL-6) in monocyte/macrophage, thus alleviated the burden of dengue immunopathogenesis." (PMID 32932762, 2020). "Generally, TNF-α, as well as IL-4, IL-6, IL-8, and IL-10, are increased in dengue patients." (PMID 33072626, 2020). "Elevated levels of IL-6 in SD as compared with patients with mild Dengue disease may indicate more pathology." (PMID 30112159, 2018). "IL-6 is also a pyrogen and induces fever in patients with dengue." (PMID 30112159, 2018). "However, within Dengue disease severity groups, IL-6 levels were decreased in DWS as compared with DF (P=0.026) as well as SD (p=0.049)." (PMID 30112159, 2018). "We determined CXCL10, IL-6 and TNFα levels in Dengue patients categorized into DF, DWS and SD." (PMID 30112159, 2018). "To investigate the relationships among endothelial glycocalyx, cytokine levels and disease severity in dengue, we conducted a prospective longitudinal study to measure serum HA, HS, IL-6, IL-10 and TNF-α concentrations in adults diagnosed with dengue and other acute febrile illness." (PMID 28393899, 2017). "Dengue patients’ sera have been found to contain high level of IL-6." (PMID 26226614, 2015). "A hallmark of severe dengue disease is the presence of elevated levels of cytokines and chemokines including IP-10, ITAC, IL-1β, IL-2, IL-6, IL-8, IL-10, IL-12, IL-13, TNFα, IFNα, IFNγ, MIF, RANTES, histamine, and complement proteins C3, C3a, and C5a within blood and tissues." (PMID 22952474, 2012). "Il-17 is the signature cytokine of the newly described T helper 17 (Th-17) cell population and has been proposed as the founding member of a new subclass of proinflammatory cytokines involved in dengue, eliciting cytokines such as Il-6, Il-8, MCP-1, GRO-α and TNF-α." (PMID 21167041, 2010). "IL-1β, IFN-γ, IL-4, IL-6, IL-13, IL-7 and GM-CSF were significantly increased in patients with severe clinical manifestations (severe dengue) when compared to mild disease forms (mild dengue)." (PMID 18578883, 2008). "Additionally, the cytokine storm characteristic of severe dengue, marked by elevated interleukin 6, tumor necrosis factor-alpha, and NS1 antigen levels, induces myocardial inflammation, microvascular leakage, and interstitial edema, further compromising cardiac function." (PMID 40546620, 2025). "However, IL-6 levels were found to be comparable between Dengue patients as compared with controls." (PMID 30112159, 2018).
dengue (continued). "The in vivo study from our group highlighted that Sinococuline treatment in dengue-infected mice reduced the viral loads in the vital organs as well as tissue proinflammatory cytokine levels like TNF-α and IL-6." (PMID 39770732, 2024). "Transfecting K562 cells in vitro with L-SIGN variants containing 7- and 9-tandem repeats confirmed that the 9-tandem repeat transfectants facilitated a higher dengue viral load accompanied by increased cytokine production (MCP-1, IL-6, and IL-8)." (PMID 38791534, 2024). "•Elevated IL-8, IL-10, IL-6, GM-CSF, MCP-1, IL-13, and IL-4 and decreased IL-12, MIP-1β on the third day after symptom onset is predictive of severe dengue." (PMID 38176525, 2024). "Our findings reveal a distinct cytokine profile (elevated IL-8, IL-10, IL-6, GM-CSF, MCP-1, IL-13, and IL-4 and decreased IL-12, MIP-1β) on the third day after symptom onset is predictive of severe dengue in secondary dengue infection." (PMID 38176525, 2024). "Recent studies have reported greater viral replication and IL-10, IL-6, and IL-1β levels in patients with a history of SDD than in individuals with a history of milder dengue disease." (PMID 39583156, 2024). "Dengue disease is characterized by an inflammatory-mediated immunopathology, with elevated levels of circulating factors including TNF-α and IL-6." (PMID 38054722, 2024). "As part of the host immune response, various cytokines, including interleukin (IL)-2, IL-6, tumor necrosis factor (TNF)-α, and interferon (IFN)-γ, contribute to severe dengue." (PMID 38306389, 2024). "TNFα, IL6 and IL8 are known to alter the vascular permeability of capillaries, triggering cases of vascular leakage in dengue." (PMID 37162062, 2023). "In another published study performed on a mouse model, recombinant dengue NS1 produced in human embryonic kidney (HEK) 293 cells or in S2 cells was able to stimulate TNF-α and IL-6 three days after intravenous administration." (PMID 36674524, 2023). "Several cytokines, including TNF-α, IL-6, IL-10 and IFN-γ, have been proposed as potential predictors of dengue severity." (PMID 36674524, 2023). "According to some studies, IL-1 β IL-6, and IFN-α levels were significantly higher in patients with severe dengue compared to those with mild dengue, which were considered as potential predictors of severe dengue infection." (PMID 37024713, 2023). "Several studies have found that IL-6, IL-17A, IFN-α, IL-1β, IL-10, and TNF-α play different roles in dengue disease, but we didn't know which factor play key roles or even correlated with IL-37b and other factors." (PMID 37024713, 2023). "More specifically, pro-inflammatory cytokines TNF-α, IL-1β, IL-6, and anti-inflammatory cytokine IL-10 have been shown to be elicited in DHF patients, and in dengue two-hit mouse models." (PMID 37298220, 2023). "We showed that IFN-α, IFN-γ, TNF-α, IL-6, MCP-1, IL-2, IL-4, and IL-10 production was higher in patients with dengue than in those with AFI." (PMID 38003826, 2023). "Within dengue severity IL-1β, IL-10 (Th1/2), and IP-10 (Th1) have been upregulated in DHF/DSS than DF, and IL-6 (Th1/Th2) and IL-17A (Th17) in DHF than DSS." (PMID 34447698, 2021). "In dengue severe cases an increase of pro inflammatory and vasoactive cytokines as IFN-γ, TNF-α, IL-1, IL-6, IL-8 IL-10, CCL2 (MCP-1) and CCL5 is usually observed." (PMID 33692368, 2021). "In our study, higher plasma levels of the proinflammatory cytokines TNF-α, IL-6 and IL-18, and the anti-inflammatory cytokine IL-10 and the chemokines CXCL8/IL-8, CCL2/MCP-1 and CXCL10/IP-10 were found in the dengue patients compared to the healthy controls." (PMID 34578370, 2021). "An earlier report also demonstrated synthesis of TNF-α, IL-6, and IL-10 from circulating B cells, monocytes, and mDC in PBMC of pediatric dengue patients; culture supernatants from these purified B cells activated allogeneic T cells." (PMID 34335578, 2021).
dengue (continued). "Previously our study also demonstrated that a high level of IL6 and vasodilation agent vascular endothelial growth factor (VEGF) were noted in severe dengue patients." (PMID 33436908, 2021). "Our further analysis showed a strong correlation of the plasma Gal-9 levels with prominent mediators of cytokine storm (IL-6, TNF-α, MCP-1, IP-10, and MIP-1α) and CRP as reported in dengue fever." (PMID 33947753, 2021). "Early studies have shown that ADE of the dengue virus infection downregulates the production of IFN-β, IFN-γ, TNF-α and IL-12, and upregulates the production of IL-6 and IL-10." (PMID 32046249, 2020). "Doxycycline was the more effective tetracycline in the reduction of IL-6 and TNF-α in patients with dengue fever." (PMID 33142770, 2020). "The next step was to quantify the serum levels of IL-1β, IL-6, IL-18, IL-10, TNF-α and CRP, as indicators of the inflammatory status in the dengue patients." (PMID 30901375, 2019). "We investigated the association of circulating levels of cytokines such as Interleukin (IL)-6, tumor necrosis factor (TNF)-alpha and CXCL-10 in Dengue patients with differing severity of disease." (PMID 30112159, 2018). "Infected mice by dengue showing increased TNF-a, IFN-g and IL-6 levels, which were recognized as triggers for DENV were also reported." (PMID 29301573, 2018). "Further, based on biomarker network analysis, two relevant strong axes during early stages of dengue fever were identified—a protective axis composed of TNF-α/lymphocytes/platelets, and a pathological axis IL-2/IL-6/monocyte/prothrombin time/viremia." (PMID 30568659, 2018). "Serum concentrations of IL-2, IL-4, IL-6, IFN-γ, TNF-α, IL-17, and IL-10 were determined in dengue patients at 6 or 7 days of fever onset and were compared with values obtained in a group of healthy controls." (PMID 28827898, 2017). "In agreement, simultaneous increase of IL-6 and IL-10 in DHF is indicative of the dysregulated immune response that leads to the progress of dengue severity." (PMID 28827898, 2017). "In our previous study, several genes involved in the TLR6 pathway have been found to be significantly up-regulated during dengue virus infection in K562 cells on day 3 post-infection which include TLR6, IL-6, TNF-α and CD80." (PMID 26226614, 2015). "Among those that responded, DV2-infected wild-type mice secreted higher amount of IL-6 compared to that of the DV2-infected TLR6-/- mice, indicating that TLR6 activation contributed to the IL-6 expression during dengue virus infection." (PMID 26226614, 2015). "Blocking of TLR2 and TLR6 also reduced the amount of IL-6 produced by PBMC during dengue virus infection, this suggested that TLR2 and TLR6 are activated during dengue virus infection and this activation led to increase in IL-6 secretion." (PMID 26226614, 2015). "Elevated serum levels of an ever increasing list of soluble mediators (such as TNFα, IL-6, C5a, VEGF, MMP-9 and others) have been measured in DHF/DSS patients and represent hallmarks of severe dengue." (PMID 24699622, 2014). "In contrast, levels of IL-6, IL-8, HGF and G-CSF were significantly increased in severe dengue compared to uncomplicated disease." (PMID 23717702, 2013). "High levels of pro-inflammatory cytokines and chemokines, including TNF-α, IL-6, IL-8, CCL2/MCP-1 and IFN-γ, have been reported in patients with severe dengue disease." (PMID 21206747, 2010). "Previous studies have shown that IL-6 and IFN-γ are elevated systemically in patients with dengue or in experimental models of the infection." (PMID 21206747, 2010). "Early measurement of these cytokines IL-6 and IL-8 helps distinguish severe from non-severe dengue among patients presenting with warning signs." (PMID 42075761, 2026). "IL-6 and IL-8 levels were significantly elevated in severe dengue patients when compared to non-severe dengue patients on Day 1 and Day 4, followed by a decline on Day 8, corresponding with clinical recovery." (PMID 42075761, 2026).
dengue (continued). "While immunomodulators (such as IL-6 inhibitors or tumor necrosis factor alpha (TNF-alpha) blockers) show promise in other inflammatory conditions, their use in severe dengue remains investigational, with limited preliminary data and concern about potential hemorrhagic complications." (PMID 40385752, 2025). "Patients with severe dengue disease and those with acute Japanese encephalitis exhibited excessively high levels of proinflammatory cytokines, known as a cytokine storm, including GM-CSF, TNF-α, IL-3, IL-6, and IL-8/CXCL8." (PMID 39972499, 2025). "Moreover, high serum levels of TNF-α, IL-1β, IL-6, CXCL-8/IL-8, and IL-10 correlated with severity of the disease in dengue patients, showing a preponderant role of NF-kB-dependent inflammatory response in dengue immunopathogenesis." (PMID 40934228, 2025). "The proinflammatory markers IL-6 and CRP were elevated in patients with anti-SARS-CoV-2 and dengue IgG antibodies compared with those with only anti-dengue IgG antibodies, highlighting the potential role of anti-SARS-CoV-2 antibodies as cross-reactive antibodies." (PMID 41583452, 2025). "Additionally, these two cell types exhibit elevated expression of cytokines and chemokines such as IL-6 and RANTES, which align with the heightened levels of these molecules observed in severe dengue patients." (PMID 38654034, 2024). "It has been shown earlier that in Dengue virus infection, a PCSK9 inhibitor could interfere with the production of IL-6, thereby reducing the inflammatory response." (PMID 37068045, 2023). "Since the levels of TNF-α, IL-6, and SOCS3 in the blood are higher in dengue-infected patients with hemorrhagic fever or shock (severe dengue) than those in patients with fever only, it suggests that overt inflammatory responses are detrimental to DENV-infected hosts." (PMID 36930690, 2023). "Furthermore, an imbalance of IL-10 and IL-6, and SOCS1/3 has been observed in patients with severe dengue virus infection." (PMID 37376550, 2023). "High expression of IL-6, IL-10, and IFN-α in DF patients was consistent with previous studies which showed that infection with dengue virus leads to elevated levels of these cytokines which are significantly increased in plasma of dengue patients." (PMID 37024713, 2023). "Based on the extensive literature on serum cytokines in dengue patients that implicates these soluble mediators in protection/severity, we chose to query TNF-α, IP-10, IL-6, and IL-10 from monocytes and granulocytes along with TNF-α, IP-10, IL-10, and IFN-γ from NK and NKT cell subsets." (PMID 34335578, 2021). "Therefore, increased IL-18 and IL-8, probable increased IL-6 and TNF-α together with decreased IFN-γ and RANTES in acute SDD patients resemble cytokine involvement in severe dengue progression." (PMID 34734091, 2021). "Thus, we examined the impact of AQCH drug substance treatment in the secondary dengue AG129 model on serum viremia as well as markers of small intestinal pathology, viz., viral load, vascular leakage, and TNF-α and IL-6 levels." (PMID 34912307, 2021). "In addition, our study found a positive association between APRI values and the levels of pro-inflammatory cytokines, chemokines and coagulation mediators (IL-6, IL-18, CXCL10/IP-10 and TFPI) in dengue patients." (PMID 34578370, 2021). "As in our previous studies, the dengue patients had high plasma levels of the cytokines TNF-α (p < 0.001), IL-6 (p = 0.005), IL-10 (p < 0.001) and, IL-18 (p = 0.001) and the chemokines CXCL8/IL-8 (p < 0.001), CCL2/MCP-1 (p < 0.001), CXCL10/IP-10 (p = 0.001) compared to healthy controls." (PMID 34578370, 2021). "More recently, MT has been reported among dengue patients and levels of LPS were accompanied with progression of dengue disease as LPS has been found to act along with DENV in triggering IL-6, PAF, and TNF-α." (PMID 33014899, 2020).